CRP (C-reactive protein)
Diseases named in the same sentence as CRP in open-access papers (continued):
Sharing a sentence is not in itself a finding about the gene and the disease.
synovitis (continued). "We also found that synovial/serum CRP ratio in partial CR stifles was correlated with progressive CrCL fiber tearing, supporting the concept that CRP reflects severity and progression of synovitis/OA and, additionally, non-contact complete CR in dogs." (PMID 27575050, 2016). "Normal synovial fluid CRP levels have not been reported for the dog and we did not identify a significant correlation with histologic or macroscopic assessment of synovitis." (PMID 24892866, 2014). "In this study, we found significant correlations between synovial MMP-3 and serum MMP-3, CRP, or ESR and significant correlation between serum MMP-3 and synovitis score with high sensitivity of serum MMP-3 in diagnosing high grade or low grade synovitis by ROC curve." (PMID 25147433, 2014). "Additional inclusion criteria were elevated C-reactive protein (CRP), sedimentation rate, ultrasound-verified synovitis, no cancer-related findings on an abdominal (CT), and chest X-ray to increase specificity as described by the ACR 2012 classification criteria." (PMID 38793033, 2024). "In the present study, lack of correlation between pain and hs-CRP or cytokines may indicate contribution of factors other than synovitis to the development of pain in KOA." (PMID 31814935, 2019). "However, severity of stifle synovitis in dogs with CR is not significantly related to serum and synovial fluid CRP, INFγ, and TNFα." (PMID 24892866, 2014). "One of these was an 82-year-old man who presented with a 6-week history of synovitis (RF negative, anti-CCP antibody negative, CRP 51 mg/l); the other was a 70-year-old woman who presented with a 10-week history of synovitis (RF positive, anti-CCP antibody positive, CRP 25 mg/l)." (PMID 15987480, 2005). "Positive CRP (>3mg/dL) was numerically frequent among patients with PsC with subclinical synovitis (respectively, 5/14 [36%] vs 5/34 [15%], p=0.13) but was equally common among patients with PsA with or without subclinical synovitis (respectively, 6/29 [21%], vs 9/23 [39%], p=0.15)." (PMID 37034375, 2022). "In order to determine whether miRNA expression can be used as a biomarker to predict disease development, blood samples were also taken from a cohort of 10 “at-risk individuals” who present with joint pain (arthralgia), but do not show clinical signs of synovitis or raised CRP." (PMID 33746971, 2021). "TNCC in the stable partial CR stifle, synovitis severity in the complete CR stifle assessed arthroscopically, T lymphocyte numbers and proportions in the peripheral circulation, normalized CrCLd in the partial CR stifle, and serum CRP at diagnosis were not correlated with second CR." (PMID 27575050, 2016). "Both patients were negative for ACPA and RF; however, the synovitis, ESR, and CRP status of the patients were not mentioned, and therefore, RA diagnosis cannot be excluded." (PMID 36169251, 2022). "In addition, synovitis identified by ultrasound correlated with the inflammatory biomarkers ESR and CRP but the presence of erosions did not correlate with the biomarkers." (PMID 39731440, 2024). "Interestingly, the tenosynovitis subscores correlated strongly with the synovitis subscores irrespective of contrast enhancement, but not with erosion, osteitis, JSN, CRP levels, or DAS-28." (PMID 35204555, 2022). "In the regression analysis, predicting the value of the calprotectin for PD synovitis was not affected by adding other parameters such as sex, age, duration of disease, and ACPA positivity, but the predictive value of CRP was not significant in multivariate analysis." (PMID 34386702, 2021). "Change in DAS28(CRP) after 14 weeks of infliximab treatment correlated with change in synovial Ktrans in the MCPs (0.33 (0.03; 058) but not the wrist and similarly with change in RAMRIS-synovitis in the MCPs (0.39 (0.10–0.62)) but not the wrist." (PMID 29236711, 2017).
synovitis (continued). "Similar analyses attempting to derive a gene signature using disease activity endpoints RAMRIS osteitis, RAMRIS synovitis, and DAS28(CRP) revealed no deviation from random expectation in Q-Q plots and no improvement in prediction of 14-week change in disease activity." (PMID 25504080, 2014). "Indeed, the percentage of Th17 cells, but not Th1, in SF positively correlated with CRP (r = 0.51, p = 0.04) and local PDUS-defined synovitis (r = 0.61, p = 0.002)." (PMID 20824142, 2010). "In this context, the present finding that local synovial features are correlated with systemic inflammatory parameters such as CRP and ESR strengthens the concept that peripheral synovitis, although not present in all SpA patients, contributes significantly to disease severity." (PMID 15743484, 2005). "Therefore, it has been suggested that CRP serum levels and, by extension, disease activity scores containing this APR are not sensitive markers of inflammation (synovitis) in patients treated with anti-IL-6R or JAKi, in contrast to other biological therapies, such as TNF inhibitors." (PMID 35054349, 2022).
rheumatic diseases (97 papers, 2008 to 2026). "Advanced age, elevated CRP, alcohol abuse, and rheumatic diseases are risk factors for bacterial and/or fungal detection in blood mNGS." (PMID 37301921, 2023). "To identify the causes of CRP elevation, we retrospectively investigated if patients had typical inflammatory complications; active infections, other active malignancies, and collagen disease." (PMID 35614177, 2022). "CRP is a hallmark of inflammation and serves as a surrogate marker for the inflammatory activity in many rheumatic disorders." (PMID 32185341, 2019). "C-reactive protein levels were significantly associated with the presence of rheumatic disease." (PMID 38713410, 2024). "To identify the causes of the elevated CAR (i.e. high CRP and/or low Alb), we focused on active infections, fever of 38.0 °C or more, active malignant tumor, collagen disease, and low eGFR < 45 ml/min/1.73 m2 at diagnosis as typical complications effecting high CAR." (PMID 35614177, 2022). "It is worth mentioning that, as occurs with other rheumatic diseases, the current tools used to predict the individual’s absolute risk for CV disease (such as lipid profile, CRP or other inflammatory markers) were found to underestimate the actual CV risk of patients with axSpA12." (PMID 30213986, 2018). "Therefore, its correlation with sialylated glycoproteins and additionally with CRP can suggest the FSA reflects the abnormalities in glycosylation of protein caused by activity of inflammation during rheumatic diseases." (PMID 24346772, 2014). "Routine laboratory tests—such as full blood count, C-reactive protein, erythrocyte sedimentation rate, and serum autoantibodies—assist in excluding infectious or rheumatologic disorders." (PMID 40941768, 2025). "Inflammatory markers such as CRP and ESR are commonly elevated across various rheumatic diseases due to their association with systemic inflammation." (PMID 40095875, 2025). "In rheumatic disorders, individualized cardiovascular risk management is made possible by combining inflammation-sensitive methods like CAC score, biomarkers (such as hs-CRP and IL-6), and sophisticated imaging." (PMID 40937212, 2025). "Similar to ESR and CRP, other parameters recognized as activity measures in rheumatic diseases, such as decreased C3 and C4 or increased fibrinogen concentration did not correlate with the occurrence of CTS in the studied group." (PMID 38969943, 2024). "Risk factors affecting mNGS bacterial and fungal test results included age, C-reactive protein, alcohol abuse, and rheumatic diseases." (PMID 37301921, 2023). "C-reactive protein (CRP) is a general inflammatory biomarker for a wide spectrum of diseases, including cardiovascular and rheumatic disorders." (PMID 35884911, 2022). "ESR and CRP are extensively used in the diagnosis and follow-up of rheumatic diseases, infections, and malignities." (PMID 35685583, 2022). "Patient’s blood tests: blood routine, liver and kidney function, and rheumatism-related indicators (including antinuclear antibody profile, anti-neutrophil cytoplasmic-related antibodies, rheumatoid factor, and high-sensitivity C-reactive protein) were normal." (PMID 35126451, 2021). "In this study, ESR level was positively correlated with CRP level, which is in line with previous results from some inflammatory diseases such as rheumatic disease." (PMID 34840450, 2021). "Synovial fluid ADA measurement, in association with C-reactive protein (CRP) and erythrocyte sedimentation rate (ESR) levels, makes it possible to distinguish OA from other rheumatic diseases, like RA." (PMID 32984382, 2020). "The results of this study showed that galectin-3 had a high diagnostic specificity in all rheumatic diseases accompanied by diagnostic sensitivity placed between ESR and CRP values." (PMID 33076422, 2020). "Different studies described a positive correlation between systemic chemerin and CRP in various chronic inflammatory diseases, including rheumatic diseases." (PMID 33192583, 2020).
rheumatic diseases (continued). "Synovial ADA fluid measurement, in association with CRP and ESR levels, can distinguish OA from other rheumatic diseases, like RA." (PMID 32984382, 2020). "Although changes in the CRP levels are considered as a gold standard to evaluate therapy in rheumatic diseases, some studies have shown controversial role of CRP level as a biomarker for disease activity." (PMID 29744553, 2018). "The average disease duration, ESR, CRP, total joint pain, and the swollen joint counts were also calculated for certain group of patients with rheumatic disease." (PMID 30046600, 2018). "The C-reactive protein (CRP) level was elevated in all four patients with rheumatic disease, but was within the normal range in the one patient with renal disease." (PMID 30285859, 2018). "C-reactive protein (CRP) is an acute phase reactant that has been used as a marker of systemic inflammation in rheumatologic disorders." (PMID 25154373, 2014). "Inflammation in SLE is in contrast to inflammation in other rheumatic diseases characterized by elevated ESR while CRP often remains low." (PMID 18234104, 2008). "However, in ICIs-related polymyalgia-like syndrome, inflammatory markers (erythrocyte sedimentation rate, C-reactive protein) are usually lower than in the primary rheumatic disease." (PMID 36981837, 2023). "ESR and CRP are commonly used to evaluate the activity of rheumatic diseases." (PMID 36369177, 2022). "The results of laboratory tests, including routine blood analyses; liver, renal, and thyroid function; ion concentration; erythrocyte sedimentation rate; homocysteine, vitamin B, and C-reactive protein levels; and immunological biomarkers of rheumatic disease were unremarkable." (PMID 35721475, 2022). "Different DNA and RNA aptamers and their modified analogs have been generated against protein biomarkers related to rheumatic diseases, from general markers such as C-reactive protein, TNFα, interleukins, and their receptors, to more specific proteins such as members of the WNT signaling pathway." (PMID 33266394, 2020). "CRP is a biomarker of inflammatory activity in some rheumatic diseases." (PMID 33348892, 2020). "The aim of this observational, prospective, pilot study was to investigate whether salivary concentrations of CRP and IL-6 correlate with those in serum and with the clinical course of a rheumatic disease." (PMID 30043213, 2018). "The main observation of this exploratory study was that the salivary concentrations of CRP in patients with rheumatic disease correlated significantly with those in serum and paralleled changes in the disease activity as reflected both by clinical and standard biochemical criteria." (PMID 30043213, 2018). "Therefore, the measurement of salivary CRP could be of potential use for the assessment of the rheumatic disease activity." (PMID 30043213, 2018). "Our data indicate that salivary CRP could also reflect the activity of rheumatic disease." (PMID 30043213, 2018). "Similar correlations between serum S100A8/A9 levels and CRP, ESR, and ferritin were already established in other rheumatic diseases." (PMID 38672106, 2024). "Recent works in the scientific literature reported the role of C reactive protein to albumin ratio (CAR), neutrophil to lymphocyte ratio (NLR) and platelet to lymphocyte ratio (PLR) as biomarkers of disease activity in rheumatic diseases." (PMID 38886765, 2024). "Conventional inflammatory markers such as CRP and ESR have been extensively explored and are correlated with disease activity in rheumatic diseases." (PMID 37959388, 2023). "CRP and ESR are markers of the severity of common rheumatic diseases, higher CRP and ESR concentrations in the respiratory involvement subgroup suggest more inflammation and disease activity." (PMID 35676691, 2022).
rheumatic diseases (continued). "The three meta-analyses published attempted to provide conclusions on the efficacy of probiotics in patients with inflammatory rheumatism, with disease activity score in 28 joints (DAS28) and C-reactive protein (CRP) as the common primary endpoints." (PMID 35057535, 2022). "The median of ESR, CRP, and PLT concentrations in these rheumatic diseases were also significantly higher compared to the controls (except for PLT in SLE, P=0.822), whereas the median of Hb was lower in comparison to healthy subjects." (PMID 33927551, 2021). "After 24 months, three out of four patients had a moderate response measured using European league against rheumatism (EULAR) parameters, erythrocyte sedimentation rate (ESR), C reactive protein (CRP), disease activity score (DAS) 28, and VAS score." (PMID 33732263, 2021). "Although CRP is frequently evaluated in clinical practice to assess the activity of rheumatic diseases, NLR was shown to be more valuable than CRP to assess disease activity in RA." (PMID 32860454, 2020). "The traditional inflammatory markers (CRP and ESR) are recommended for the assessment of rheumatic diseases, infectious diseases, and several cancers in clinical practice." (PMID 32164741, 2020). "Laboratory testing and imaging were performed for diagnosing and assessing diseases activity for children with rheumatic disorders and these including ESR, CRP, ALT, AST, LDH and autoimmune markers." (PMID 32245494, 2020). "The positive predictive value (PPV) of galectin-3 was higher than PPV of CRP and ESR in all rheumatic diseases." (PMID 33076422, 2020). "CRP, ESR, the platelet count, and serum VEGF were significantly higher (p < 0.001) in individuals with rheumatic disease than in the controls." (PMID 27906058, 2016). "The diagnostic power of TSA and FSA resulting from ROC analysis indicates that these tests have lower sensitivity, specificity, positive and negative predictive values, and the area under the ROC curves than that of CRP and anti-CCP in rheumatic disorders." (PMID 24346772, 2014). "Erythrocyte sedimentation rate (ESR) and serum C-reactive protein (CRP) are commonly used inflammatory biomarkers to monitor disease activity in rheumatic diseases, but they are not very sensitive or specific." (PMID 41342238, 2025). "CRP and ESR are commonly used clinical inflammatory markers that reflect changes in the inflammation level of patients and have been utilized to help assess the inflammatory activity in various rheumatic diseases." (PMID 39835879, 2025). "NLCM was shown to be helpful in lowering pain, fatigue, and CRP, which implies that NLCM may be a reference in the provision of tailored care for those affected by rheumatism." (PMID 38903826, 2024). "Although not statistically significant, patients with rheumatic disease also had higher CRP levels at presentation." (PMID 39066867, 2024). "There are other pathological or nonpathological processes that increases the CRP level, such as in patients with infections, malignancies, inflammations, and rheumatologic disorders." (PMID 38905361, 2024). "We often experience AML patients with high CRP despite the absence of infection, other malignant tumor, and collagen disease." (PMID 35614177, 2022). "Moreover, critical proinflammatory cytokines such as IL-6, C-reactive protein (CRP), and tumor necrosis factor (TNF-α) not only play a pivotal role in the inflammatory cascade and evolution of rheumatic diseases but also are independent predictors of CVD." (PMID 34504395, 2021). "The analysis of variance revealed that rheumatic diseases did not affect the galectin-3 concentration (H = 0.395, p = 0.821), CRP (H = 4.798, p = 0.091), PLT (H = 5.061, p = 0.080), and HGB (H = 3.935, p = 0.140), but effect the ESR (H = 13.001, p = 0.002)." (PMID 33076422, 2020).
rheumatic diseases (continued). "Levels of S100A8/A9 and S100A12 have been considered sensitive biomarkers of disease activity in rheumatologic disorders, and may be even more reflective of the degree of inflammation than erythrocyte sedimentation rate (ESR) and C-reactive protein (CRP)." (PMID 31948488, 2020). "Such nonspecific markers as CRP or TNFα serve as precursors of complications and are decreased during remission or low activity of any rheumatic disease." (PMID 33266394, 2020). "Inflammatory markers characteristic of inflammation in rheumatic diseases including ESR and CRP were found to show a statistically significant correlation (p < 0.0005 and p < 0.005, respectively) with the scintigraphic uptake ratio, while showing a correlation coefficient value." (PMID 32161274, 2020). "In conclusion, salivary concentrations of CRP, but not of IL-6, in patients with rheumatic disease significantly decrease over the course of successful anti-TNFα therapy and parallel changes in the disease activity." (PMID 30043213, 2018). "All acute-phase proteins in patients with rheumatic diseases were significantly changed in comparison with the controls: positive acute-phase proteins (CRP, AGP, HP and AAT) were elevated and the negative (TRF)—decreased." (PMID 24346772, 2014). "Some diseases that could affect the level of CRP, such as infectious diseases, rheumatic diseases, connective tissue diseases, etc., were not considered in the present study." (PMID 35807747, 2022). "The limitations of our study are that the suitability of patient VAS for patients without rheumatic diseases is unknown, and the lack of CRP and radiographic joint evaluation data of those patients." (PMID 32943723, 2020). "ESR and CRP are usually used to judge inflammatory activity in rheumatic diseases; nevertheless, it is well known that no serological marker is good enough to reflect the ongoing inflammation in the SpA such as AS and this may justify our findings." (PMID 28379663, 2017). "Salivary CRP but not IL-6 could be of potential use for monitoring the rheumatic disease activity." (PMID 30043213, 2018). "Correlation coefficient analyses indicated that the baseline serum CRP level was moderately correlated with the baseline SRS22 pain score in the prefrail/frail group, while none of them had inflammatory disorders or collagen diseases (r = −0.508)." (PMID 38673567, 2024). "Additionally, the one non-glycosylated protein, CRP, also correlated with TSA and FSA, and this may suggest that both TSA and FSA can be treated as a non-specific markers of inflammation during rheumatic diseases (RA and SSc)." (PMID 24346772, 2014).